GLI1 (GLI family zinc finger 1)
Diseases named in the same sentence as GLI1 in open-access papers (continued):
Sharing a sentence is not in itself a finding about the gene and the disease.
tumor (continued). "In this trial, tissue mRNA analysis of pre-treatment and post-treatment GLI1 expression via RNA in situ hybridization (using RNAScope technology) is planned to better evaluate the dynamics of the Hedgehog pathway in the tumor microenvironment." (PMID 26426053, 2015). "In contrast to above mechanism, our recent studies have revealed a tumor-specific role for aberrant GLI1 in regulation of S phase checkpoint." (PMID 26633513, 2015). "Results showed a reduction in tumour cell proliferation (as measured by Ki67 staining) of 45% (P = 0.04), Hedgehog pathway activity (as measured by GLI1 mRNA) of 65% (P = 0.03), and reduced tumour area of 24% (95% CI, 18.2–30.0%)." (PMID 25932045, 2015). "Inhibition of GLI1 in several tumor cell lines originated from different tissues induced replication associated DNA damage as indicated by γH2AX and attenuated tumor cell growth." (PMID 26633513, 2015). "Analysis of GLI1 immunoreactivity in a small cohort of MPM patients revealed heterogeneous expression in both tumor and stroma fractions." (PMID 26184317, 2015). "This suggests HH/GLI1 signaling works synergistically through distinct novel pathways during tumor initiation and growth." (PMID 25352983, 2014). "It was found that Gli1 protein expression was positive in 57 out of 63 tumor tissues (90.48%), including 17 (26.98%) highly positive (+++) cases." (PMID 25289083, 2014). "Cox regression analysis revealed that there was a significant correlation between Gli1 expression and tumor invasiveness, including histological differentiation, portal vein tumorous thrombogenesis, lymph node invasion and TNM stage." (PMID 25017332, 2014). "Knockdown of GLI1 expression in claudin-low cell lines resulted in reduced cell viability, motility, clonogenicity, self-renewal, and reduced tumor growth of orthotopic xenografts." (PMID 25252859, 2014). "Expression of GLI1 and GLI3 mRNA was strongly correlated, and their overexpression, especially that of GLI1, was found to be predictive of aggressive tumor behavior." (PMID 25103784, 2014). "The tumours from which the cell lines were derived have been assigned to MB molecular subtypes using IHC for β-catenin, Gli1, NPR3 and KCNA1, and sequencing of the β-catenin gene (CTNNB1)." (PMID 24887326, 2014). "While previous studies have highlighted the ability of ectopic GLI1 expression to form tumors in vivo, we wanted to investigate the effects of GLI1 knockdown on the tumor-forming abilities of claudin-low MDA.MB.436 cells as orthotopic xenografts." (PMID 25252859, 2014). "Given the emerging importance of protein kinase CK2 and Hh/Gli1 signaling in tumor initiation and progression, our findings provide important new evidence for the potential benefits of CK2 inhibitors." (PMID 25422081, 2014). "While much of our data were collected using the ER-positive MCF7 and HCC1428 cell lines, we were able to observe upregulation of Gli1 in many different primary human tumor tissue samples, suggesting the relevance of this pathway in primary tumors." (PMID 24889938, 2014). "Loss of GLI1 was associated with a significant decrease in expression of FAS/FASL, leading to lower apoptosis levels and increased tumor progression." (PMID 25352983, 2014). "Activation of TGFβ induced GLI2 expression, and subsequent GLI1 activation, is associated with epithelial to mesenchymal transition (EMT), tumor growth, and metastasis (Javelaudet al., 2012)." (PMID 25352983, 2014). "Cox regression analysis showed that there was a significant correlation between Gli1 expression and tumor invasiveness, including histological differentiation, portal vein tumorous thrombogenesis, lymph node invasion and TNM stage." (PMID 25289083, 2014). "We investigated the effects of GLI1 knockdown on aggressive characteristics of claudin-low tumor cells, including proliferation, migration, and anoikis." (PMID 25252859, 2014).
tumor (continued). "The correlation between GLI1 and Cav-1 was confirmed in tumor specimens from HCC patients and Cav-1 was found to be associated with poor prognosis after hepatic resection." (PMID 24454730, 2014). "Spearman's correlation analysis of IHC demonstrated that Sufu in tumor tissues inversely correlated with Gli1 expression." (PMID 25373737, 2014). "Western blot analyses of tumor tissues revealed that treatment with GANT61 indeed down-regulated Gli1 and Gli2 in tissues." (PMID 24533083, 2014). "Inhibition of the HH pathway in PDAC cell-based xenograft models through Smo inhibition has been shown to reduce GLI1 activity and tumor growth (Feldmannet al., 2007;Thayeret al., 2003;Yauchet al., 2008)." (PMID 25352983, 2014). "Gli1 protein was detected in 57 of the 63 tumor tissues (90.47%), including 17 (26.98%) highly positive (+++) cases." (PMID 25017332, 2014). "In the current study, statistical analysis showed there was a significant correlation between Gli1 expression and tumor invasiveness." (PMID 25289083, 2014). "In HCC, GLI1 expression is significantly correlated with tumor size and TNM stage; GLI1 expression is high in patients with early recurrence and poorer overall survival." (PMID 24678763, 2014). "IHC analysis confirmed that Sufu plasmid enhanced Sufu expression and reduced Gli1 expression and nuclear accumulation in tumor, compared with control group." (PMID 25373737, 2014). "This system models paracrine Hh signaling whereby the MiaPaCa tumor cells secrete Hh ligand to surrounding stromal cells leading to enhanced Gli1 transcription." (PMID 24608250, 2014). "Higher GLI1 mRNA expression was demonstrated to be an independent prognostic factor for poor patient prognosis (P = 0.0030, HR = 3.1 (1.5-6.2)) as well as tumor differentiation (well vs. poor) and tumor stage." (PMID 25103784, 2014). "Here, we use mRNA encoding human tumor inducers (Gli1, XRel3, KRAS) in Xenopus laevis embryos to initiate growth of tumor like structures (ITLS) that highly resemble classic tumors." (PMID 24830454, 2014). "And the data of in vivo experiments also showed that GLI1 promoted tumor xenograft growth significantly, which verifies the oncogenic effect of GLI1 on HCC further." (PMID 24454730, 2014). "The Gli1 transcription factor is an important mediator in the Hedgehog pathway that regulates genes essential for tumor progression." (PMID 25069516, 2014). "Our lab has developed a novel small molecule, the Gli inhibitor (Gli-I), which specifically inhibits Gli1 and Gli2 transcriptional activity, resulting in dramatic cytotoxicity in tumor cells that are Gli activity dependent." (PMID 23483902, 2013). "We investigated CloP- and ChiP-initiated tumor xenografts for expression levels and localization of pAkt, Gli-1, and β-catenin as markers of signaling pathways that are directly involved in self-renewal." (PMID 23468473, 2013). "We further confirmed the role of SHH signaling in dying tumor cell stimulated living tumor cell growth by using shRNA to knockdown Gli1 expression in feeder cells." (PMID 23762282, 2013). "These GLI1-induced tumours exhibit expansion of a population of epithelial cells expressing the progenitor cell markers keratin 6 and BMI-1." (PMID 23436775, 2013). "The average expression level of gli2 was 2.4 fold as high in tumor tissues as in patient normal pleura (p<0.01), whereas gli1 levels were statistically comparable." (PMID 23483902, 2013). "SUFU acts as a classic tumor suppressor gene, with mutations leading to the inability of SUFU to transport GLI1 out of the nucleus to the cytoplasm, thereby resulting in aberrant activation of HH signaling in MB." (PMID 23826113, 2013). "A significant increase in tumour-free survival was observed in NRP2-depleted cells compared to control cells providing evidence for the importance of NRP2 in GLI1-mediated tumourigenesis." (PMID 23436775, 2013).
tumor (continued). "To further confirm the roles of SHH signaling on dying tumor cell stimulated living tumor cell growth, we tested another Gli1 antagonist (Gant61)." (PMID 23762282, 2013). "The results demonstrated that Gli1 expression in the stroma was specifically and significantly reduced within 24 hours of IPI-926 treatment, while expression of Gli1 in tumor cells was unaffected." (PMID 23303278, 2013). "The independent role of Gli1 expression as marker of poor prognosis was sustained by multivariate analysis, after adjusting for residual tumor at surgery and chemosensitivity." (PMID 23555905, 2013). "In a mouse model of BCC, it was suggested that the degree of expression of GLI1 or GLI2 has a critical impact on the development of BCC tumours." (PMID 24163262, 2013). "While analyzing these skin lesions by H&E, we noticed the trichilemmal keratinization and strong expression of ALK and GLI1 within the tumours." (PMID 24163262, 2013). "In vivo experiments using transgenic mice overexpressing GLI1 in the mammary gland show an increase in the tumour initiation cell population, thus further supporting a role of this molecule in the regulation of this cellular compartment." (PMID 23505092, 2013). "Based on this functional defect and the marked elevation of GLI1 expression in the tumor, we conclude that PTCH1 P681L is likely to be a driver mutation." (PMID 24368541, 2013). "Defining the impact of the tumour microenvironment on this molecular process and identifying the entire repertoire of signalling pathways activating GLI1 will be crucial for the success of future anti-NRP2 therapies." (PMID 23505092, 2013). "A small-molecule inhibitor for Gli1 inhibited tumor cell proliferation in vitro and successfully blocked cell growth in an in vivo xenograft model using human prostate cancer cells harboring downstream activation of the Hh pathway." (PMID 23303278, 2013). "Expression of GLI1 decreased the incidence of tumour-free survival significantly demonstrating that GLI1 is sufficient to compensate for low NRP2 expression in tumour initiation." (PMID 23436775, 2013). "GLI1 expression at the peripheral area of the tumour nests was increased compared to normal epidermis." (PMID 24163262, 2013). "This decreased the tumor size by 60%, which was accompanied by inhibition of Gli1 expression in tumor tissue." (PMID 23024864, 2012). "Consistent with the prior results, tumor vascular invasion was more frequent in High GLI1 expressing HCCs than in Low GLI1 expressing HCCs (22.9% vs. 14.3%), but this difference was not statistically significant." (PMID 23185371, 2012). "Even though mutations of the SHH target gene, Glioma-associated oncogene homolog-1 (GLI1), are uncommon, approximately 90% of sporadic BCC overexpress GLI1, which contributes to tumor growth." (PMID 23284750, 2012). "In contrast, relative to the mice injected with control cells, the incidence in mice injected with tumor cells stably silenced for GLI1 was reduced to 60% (each knee is scored as an incident)." (PMID 22479615, 2012). "GLI1 mRNA was detected in 74 of 139 HCC patients and there was increased GLI1 expression in tumor compared to benign tissues in 43 (58.1%) of the HCCs." (PMID 23185371, 2012). "The GLI1 high expresser group included patients with higher GLI1 expression in tumor tissues, while the GLI1 low/non expresser group included patients with lower or no GLI1 expression in tumor tissues." (PMID 23185371, 2012). "Down regulation of the hedgehog target genes Gli1, Ptch1 and Hip was found in the tumor cells of LDE225 treated mice, and survival was prolonged in the LDE225 treated Rip1Tag2 mice." (PMID 23344019, 2012). "This is apparent in the fact that ablating GLI1 severely compromised the ability of the tumor cells to form osteolytic metastasis in an experimental model of bone metastasis." (PMID 22479615, 2012).
tumor (continued). "In order to assess the role of Hh signaling in tumor cells on their ability to elicit osteoblast differentiation, we abrogated the expression of GLI1 from the tumor cells by shRNA." (PMID 22479615, 2012). "The downregulation of the Hedgehog target gene Gli1 was demonstrated in the tumor of cyclopamine treated mice, and a significantly prolonged survival of the cyclopamine treated Rip1tag2 mice in vivo was achieved." (PMID 23344019, 2012). "We examined the effect of acute and prolonged IPI-926 treatment on stromal and tumor Gli1 expression in our ovarian xenograft model." (PMID 22140510, 2011). "Following tumor harvest, the relative expression of mouse and human Gli1 was assessed by RT-PCR using species-specific primers." (PMID 22140510, 2011). "For example, several studieshave advocated that increased epithelial GLI1 expression promotes tumour formation." (PMID 21633508, 2011). "A single dose of IPI-926 inhibited mouse stromal Gli1 transcript levels at 24 hours with unchanged human intra-tumor Gli1 levels." (PMID 22140510, 2011). "IPI-926 induces a dose dependent reduction in Gli1 mRNA expression and durable tumor remission in a murine medulloblastoma model." (PMID 22140510, 2011). "To assess the site of action of IPI-926 in our system, we analyzed Gli1 mRNA expression in both mouse stroma and human tumor cells following either acute or prolonged treatment with IPI-926." (PMID 22140510, 2011). "In contrast to what was also observed in the acute setting, moderate inhibition of Gli1 mRNA expression was observed in the tumor (p<0.03) following prolonged treatment." (PMID 22140510, 2011). "GLI1 mediates cell proliferation via activating expression of several positive regulators of cell-cycle progression, such as, inhibitors of Rb tumor suppressor, cyclins." (PMID 21119888, 2010). "In order to determine which cells were affected by cyclopamine treatment, we measured expression of Ptch1 and Gli1 mRNA, transcriptional targets of Hh signaling, in both the xenografted human tumor cells as well as the mouse stromal compartment." (PMID 20098680, 2010). "This pathway is important in proliferation and growth and GLI1 has been implicated in basal cell carcinoma in mice; more generally, abnormal activity of hedgehog-GLI is associated with a variety of tumor types." (PMID 20187943, 2010). "Accumulating evidence suggests an essential role that GLI1 plays in tumor progression and metastasis." (PMID 21119888, 2010). "Strikingly, BA treatment led to a more regional expression of GLI1 leaving large tumour areas unstained, as compared with the homogeneous GLI1 staining in untreated tumours." (PMID 20517313, 2010). "We also carried out multivariate analysis and found a significant association between advanced tumour stage (pT2 vs pT1) and increased likelihood of GLI1 overexpression in the analysed tumours (4.9 times; 95% CI 2.3 – 10.5)." (PMID 19706168, 2009). "Multivariate logistic regression analysis was carried out to evaluate the role of tumour stage, histological grade and lymph node status as indicators for GLI1 overexpression." (PMID 19706168, 2009). "A number of researchers have reported the development of HH/GLI1 cascade inhibitors as a new class of anti-tumor agent." (PMID 19575820, 2009). "A significant correlation was found between increased expression of nuclear GLI1 and tumour stage (P < 0.001) but also between increased expression of nuclear GLI1 and the lymph node status (P = 0.027) of the analysed tumours." (PMID 19706168, 2009). "It is known that GLI proteins themselves are mediators of more than just the Hh signalling pathway and overexpression of GLI1 is reported from several human tumour entities as well as benign tissues of organs like prostate or colon." (PMID 19706168, 2009). "Next we analysed GLI1 mRNA expression in a set of matched tumour and normal breast tissue samples (n = 5)." (PMID 19706168, 2009).
tumor (continued). "Several studies on GLI1 analysed potential involvement of this transcription factor in tumour developmental processes." (PMID 19706168, 2009). "One group used immunohistochemistry to detect expression Hh targets PTCH1 and Gli1 in the tumor specimens whereas we and others assessed the expression of Hh target genes by several methods: in-situ hybridization, real-time PCR and immunohistochemistry." (PMID 19943941, 2009). "In the tumours with Gli-1 nuclear expression, two were scored as (±), two were scored as (+), three were scored as (++), and none were scored as (+++)." (PMID 18475300, 2008). "Given the potential pro-metastatic consequences of STK38 inhibition, we instead targeted its downstream effector GLI1 using Glabrescione B, which potently suppressed tumor growth and induced apoptosis in both xenograft and patient-derived organoid models, particularly in STK38-high tumors." (PMID 41540036, 2026). "However, inhibiting the SHH/GLI1 pathway pharmacologically can counteract tumor-related angiogenesis." (PMID 41522355, 2026). "The contrasting methylation patterns of MGMT/NUPR1 and NDRG2/GLI1 in GBM may shed light on their opposing roles in tumor development and progression." (PMID 41596413, 2026). "This hypermethylation may lead to altered expressions of the GLI1 gene, thereby disrupting normal HH signaling and contributing to tumor development and progression." (PMID 41596413, 2026). "Our findings are consistent with prior reports of STK38 enhancing cellular sensitivity to stress-induced apoptosis, suggesting that GLI1 inhibition may synergize with STK38-driven stress pathways to induce more effective tumor cell death." (PMID 41540036, 2026). "Inhibiting the SHH/GLI1 pathway suppresses tumor growth, primarily through reduced angiogenesis." (PMID 41522355, 2026). "The dual GLI1/p16 immunohistochemical panel thus emerges as a cost-effective and practical screening approach, enabling pathologists to effectively identify and distinguish GLI1-altered neoplasms and potentially guiding subsequent molecular testing and therapeutic decisions." (PMID 39851545, 2025). "Our study found that SH downregulated the protein and mRNA expression of SHh, PTC, SMO, Gli1, and Gli2 in the Hedgehog pathway, suggesting that SH might inhibit tumor progression via suppressing the Hedgehog pathway activation." (PMID 41444284, 2025). "They mediated their effects in both stromal and epithelial cells by significantly reducing GLI1 expression in the stroma and tumor cells, although previously, canonical inhibition of the HH pathway could not be clinically confirmed." (PMID 40565349, 2025). "In cancers with PTCH1::GLI1 fusions, the normal tumor-suppressive function of PTCH1 is disrupted." (PMID 39851545, 2025). "In addition, immunohistochemical analysis of tumor tissues showed that alpha-estradiol and (R)-(−)-ibuprofen inhibited the expression of GLI1, Zeb1 and Vimentin." (PMID 40255562, 2025). "In addition to the hyperactivation of Hh signaling, tumor cells also exhibit ECs and infiltrating macrophages with elevated Shh, Ihh, and Gli1 expression, suggesting an involvement in angiogenesis and tumor metastasis." (PMID 40750730, 2025). "Given the well-documented importance of Gli1 in tumor development and progression we sought to determine whether these compounds directly targeted Gli1 or act upstream, e.g., at the level of Smoothened (Smo)." (PMID 40651614, 2025). "Additionally, IHC staining revealed decreased percentages of monocyte/macrophages, which are detected by F4/80, Ly6C or CD115 markers, in tumours with GLI1 KO or CCL20 KO cells compared to WT tumour cells." (PMID 40913253, 2025). "Nonetheless, the diagnosis of GLI1-rearranged enteric tumors can be a significant challenge because of their overlapping clinical, morphological, and immunophenotypic characteristics with various other neoplasms, leading to a broad differential diagnosis." (PMID 39851545, 2025).